IL6 (interleukin 6)
Diseases named in the same sentence as IL6 in open-access papers (continued):
Sharing a sentence is not in itself a finding about the gene and the disease.
oral cancer (continued). "The predominant genes implicated in the ten principal pathways were MAPK1, MAPK8, MAPK14, and IL6, which were observed to be linked to the MAPK signaling pathway, perhaps serving as the critical channel through which Galangin may facilitate the treatment of oral cancer." (PMID 39702881, 2024). "Several inflammatory mediators, salivary proteins, and oral microbiota are shared between inflammatory conditions of the oral cavity (IL-1, IL-6, IL-8, TNF-α), such as periodontitis, and oral cancer." (PMID 37686542, 2023). "For instance, certain inflammatory cytokines, such as IL-8, IL-6, and TNF-α, have been identified as potential biomarkers for diagnosing oral cancer." (PMID 38067304, 2023). "We found the upregulation of IL6, Ki67, c-myc, Akt, and BIRC3 genes in the oral cancer dataset-GSE30784 as well as in the analyzed head and neck statistics available at Oncomine." (PMID 36845732, 2023). "IL-6 and IL-8 have been shown to cause immunosuppression in the TME and regulate tumor progression, metastasis, and invasion; in this context, immune-based therapeutic intervention targeting IL-6 and IL-8 may represent a new therapeutic strategy in patients with oral cancer." (PMID 34063134, 2021). "Further comparisons revealed notable elevations of IL-6, IL-8, TNF-α, HCC-1, and PF-4 levels in OSCC collated to OL sample cohorts, with increases traceable from early oral cancer stages." (PMID 33924500, 2021). "In oral cancer, IL-1β enhances EMT in oral squamous cell carcinoma and dysplastic oral keratinocytes through the production of proinflammatory cytokines such as IL-6, IL-8, and GROα." (PMID 34220337, 2021). "IL-6 and IL-8 promote EMT and cell invasion, which is potentially related to the STAT3 signaling pathway in oral cancer." (PMID 34063134, 2021). "Several reports have indicated that IL-6, derived from CAFs, is involved in the shaping of the immunosuppressive TME of oral cancer." (PMID 33668218, 2021). "Specifically, TNF-α, IL-6, and PGE-2 participate in the process of submucous fibrosis, which plays a critical role in enhancing the malignant transformation of oral cancer cells." (PMID 34445474, 2021). "IL-6 also induced promoter hypermethylation of several important TSGs, namely CHFR, GATA5, and PAX6, in oral cancer cells." (PMID 32678024, 2020). "This article reviews the expression of levels of specific cytokines i.e., IL-8, IL-6 and TNF-α, their signaling pathways in the development of oral cancer, and how they are essential for the diagnosis of OSCC and updates related to it." (PMID 28397778, 2017). "CXCR4 was previously found to be involved in the production of pro-inflammatory cytokines, such as interleukin 6 (IL-6), which is increased after CXCR4 activation in microglia, human oral cancer cells, and fibroblasts." (PMID 27716214, 2016). "Besides supporting the possibility of using this compound for treating oral cancer, the neutralization of IL-6 induced by S100A9 may also function as potent anti-neoplastic agents in oral carcinogenesis, in which the stromal S100A9 plays a significant role in regulating tumor growth and metastasis." (PMID 26315114, 2015). "Previously, we reported that activation of IL-6/STAT3 signaling induced aggressive tumor behavior and EMT changes in oral cancer." (PMID 24625449, 2014). "The aim of this study was to compare salivary and serum concentrations of IL-1β, IL-6 and TNF-α in patients with oral leukoplakia, oral cancer and healthy controls." (PMID 21743397, 2012). "IL-6, TNF-α, and endothelin are established (oral cancer) pain mediators." (PMID 40144515, 2025).
oral cancer (continued). "In most cases, pro-inflammatory cytokines (IFN-γ, IL-2, IL-1α, IL-1β, TNF-α, IL-17, and IL-8), anti-inflammatory cytokines (IL-4 and IL-10), and pro-/anti-inflammatory cytokines (IL-6 and TGF-β) are unbalanced in oral cancer, resulting in an immunosuppressive environment." (PMID 37686542, 2023). "Furthermore, the data in vivo confirmed the findings in vitro and suggest that attenuating IL-6 signaling reverses EMT, CSC development, and tumor invasiveness in S. mutans-infected oral cancer cells." (PMID 36186905, 2022). "The proangiogenic and pro-inflammatory cytokines IL-1, IL-6, IL-8 and TNF-α are elevated in saliva samples of patients with oral cancer and oral precancer, so they have the potential of surrogate indicators of carcinogenic mutation from oral precancer to oral cancer." (PMID 35888762, 2022). "In patients with oral cancer, local and systemic higher levels of pro-inflammatory cytokines TNF-alpha, IL-6 and IL1-beta may contribute to tumor progression leading to a poor prognosis of the disease." (PMID 33411841, 2021). "Therefore, chrysophanol has the potential to inhibit migration/invasion and EMT through the inhibition of IL-6- and IL-8-induced activation of STAT3 in oral cancer." (PMID 34063134, 2021). "In conclusion, our findings suggest that overexpression of IL-6 and IL-8 promotes the EMT and invasion abilities of oral cancer cells through the STAT3 signaling pathway and also decreases E-cadherin expression and increases vimentin expression; these effects are abolished by chrysophanol." (PMID 34063134, 2021). "The activation of inflammatory marker IL-6 could be the vital signal responsible for the induction and over-expression of DNMT3B in oral cancer." (PMID 33369458, 2020). "The intimate contact between the buccal mucosa and the AQ during chewing induces chronic and abnormal mucosa inflammation by promoting the release of inflammatory mediators like IL-6, TNF-α, and PGE2 by oral keratinocytes, playing a crucial role in the pathogenesis of oral cancer." (PMID 28209200, 2017). "Although the expression of IL-6 mRNA was significantly induced in S100A9 xenograft tissues, there was no enhancement of IL-6 expression and downstream mediators in S100A9-expressing oral cancer monoculture." (PMID 26315114, 2015). "The data obtained from the present study revealed that the increased DNMT3b induced by IL-6, which might be mediated by the activation of STAT3 and PI3K signaling, is critical in tumor aggressiveness and prognosis of oral cancer." (PMID 24625449, 2014). "Irrespective of the role of IL-6, there is increasing evidence to support higher levels of IL-6 in the saliva of patients with oral cancer, as well as oral potentially malignant lesions, than in normal controls." (PMID 24376459, 2013). "In a model of oral cancer, resveratrol suppressed the metastasis and invasion of H-357 cells by inhibiting the activity of MMP-2 and MMP-9 and numerous inflammation mediators, e.g., NF-κB, COX-2, inducible nitric oxide synthase (iNOS), TLR4, TNF-α, interleukin-1 β (IL-1 β), and interleukin-6 (IL-6)." (PMID 39335164, 2024). "Among the most frequent cytokines investigated as candidates for OSCC biomarkers, IL-6, IL-8, TNF-α are present at higher concentration in the saliva of OSCC patients than in healthy controls and may therefore serve as basis for the development of rapid tests for early diagnosis of oral cancer." (PMID 34202728, 2021). "Although both groups exhibited increased IL-6 and CRP levels postoperatively, without significant differences, further research is needed to validate the efficacy of dexmedetomidine in oral cancer pain management." (PMID 38675500, 2024). "We evaluated the expression of IL-6 and IL-8 in human SAS and FaDu oral cancer cell lines in the presence or absence of chrysophanol." (PMID 34063134, 2021).
vitamin D deficiency (111 papers, 2013 to 2026). A nutritional condition produced by a deficiency of VITAMIN D in the diet, insufficient production of vitamin D in the skin, inadequate absorption of vitamin D from the diet, or abnormal conversion of vitamin D to its bioactive metabolites. "Vitamin D deficiency is associated with elevated inflammatory cytokines (IL-6 and TNF-α) and worse clinical outcomes in kneeosteoarthritis." (PMID 41170094, 2025). "For instance, vitamin D deficiency removes the anti-inflammatory brake, leading to higher levels of IL-6 and TNF-α and accelerating renal injury." (PMID 41142318, 2025). "Vitamin D deficiency has been linked to enhanced expression of proinflammatory interleukins such as IL-1β, IL-6, and TNF-α, which are physiological mediators of the inflammatory response and are frequently elevated in the tears of DES patients." (PMID 41157226, 2025). "There was a significantly higher IL-6 level in de novo AML patients with vitamin D deficiency (< 20 ng/ml) than those with normal vitamin D level on the 1st day of the induction chemotherapy with median values 7.59 pg/ml vs. 2.53 pg/ml and p-value of 0.001." (PMID 40671161, 2025). "In in vitro trophoblast experiments, vitamin D deficiency decreased the expression of hCG and increased the expression of tumor necrosis factor-alpha, interleukin-6, and interferon-gamma, thereby increasing the T-helper/T-cytotoxic cell ratio." (PMID 41367918, 2025). "Patients with vitamin - D deficiency (20 ng/ml andlower) had the highest mean IL-6 concentration of 325.74±393.19 pg/ml." (PMID 41170094, 2025). "Patients with vitamin D deficiency exhibited significantly higher IL-6 and TNF-α levels and worse WOMAC scores.Data shows that vitamin D deficiency is associated with increased inflammation and poorer functional outcomes in knee OA." (PMID 41170094, 2025). "Vitamin D deficiency leads to diminished production of inflammatory cytokines, including IL-1, IL-6, IL-12, IL-21, and TNF-α, while enhancing the production of anti-inflammatory cytokines, such as IL-10." (PMID 39598148, 2024). "In the context of vitamin D deficiency, there is a marked increase in IL-6 and caspase-3 expression, with fold changes of 6.5 and 8.4, respectively." (PMID 39062991, 2024). "The relationship between vitamin D deficiency and levels of IL-1β, IL-4, and IL-6 was previously shown in obese rats fed a vitamin D-reduced high-fat diet." (PMID 39310506, 2024). "Serum vitamin D deficiency is associated with higher levels of serum proinflammatory cytokines (IL-6 and IL-8), and higher levels of serum proinflammatory cytokines are associated with a greater FM impact." (PMID 38257075, 2024). "In patients with vitamin D deficiency, the increases in IL-6 and caspase-3 expression, alongside elevated levels of IL-1β and CXCL10, emphasize a pronounced inflammatory and apoptotic milieu." (PMID 39062991, 2024). "Specifically, vitamin D deficiency has been correlated to higher serum levels of IL-17 and IL-6 in OLP patients, especially in the symptomatic subset." (PMID 36786956, 2023). "It should be noted that vitamin D deficiency was more strongly correlated with increased IL-6 (r=−0.37) and CRP (r=−0.39), as well as with DI (r=−0.36)." (PMID 37558268, 2023). "Previous experimental studies have linked antiangiogenic factors with other maternal serum parameters, such as vitamin D deficiency, increased IL-6 or C-reactive protein, and decreased leptin levels." (PMID 35631313, 2022). "A study of 35 6-year-old children found that exposure to IL-6, which is found in higher concentration in outdoor traffic pollution, is closely related to vitamin D deficiency." (PMID 36530693, 2022). "For example, significantly higher levels of serum IL-6 associated with vitamin D deficiency have been described in a variety of patients with various disorders ranging from diabetes, to osteoarthritis, to HIV/AIDS, to pancreatic ductal adenocarcinoma." (PMID 35308241, 2022).
vitamin D deficiency (continued). "Significantly decreased adropin levels and significantly increased levels of proinflammatory cytokines (IL-1β, IL-6) were detected in vitamin D deficiency with the oxidative/antioxidative balance being changed in favor of oxidative status." (PMID 36326375, 2022). "Higher levels of IL-6 were observed in vitamin D deficiency suggesting a greater inflammatory response in these patients." (PMID 35155539, 2022). "Vitamin D deficiency has been associated with elevated systemic proinflammatory cytokines in pregnancy and at delivery (IL-6 and TNF-α) and low birth weight." (PMID 34836049, 2021). "We also previously showed that vitamin D deficiency was associated with a more pronounced pro-inflammatory status, including higher Interleukin (IL)-6 and C-reactive protein (CRP) in older Irish adults." (PMID 33672800, 2021). "In conclusion, severe vitamin D deficiency plays a role in painful DPN pathogenesis through elevated inflammation IL-6 and TNF-α levels." (PMID 33777989, 2021). "Vitamin D deficiency was positively associated with the elevated IL-6 and decreased eGFR, especially in the PP study group." (PMID 34576798, 2021). "The multivariate logistic analysis showed that severe vitamin D deficiency, IL-6, and TNF-α were independent risks for painful DPN after adjusting for confounding factors." (PMID 33777989, 2021). "It has been recently reported that vitamin D deficiency is associated with increased levels of IL-6 in patients with HIV infections." (PMID 34836187, 2021). "The results of this study revealed that vitamin D deficiency is associated with an increased expression of IL-33, IL-37, IL-6, TNF-α, TLRs, DAMPs, and MMPs, while vitamin D supplementation is associated with a decreased expression of the former." (PMID 34842603, 2021). "Two mechanisms would explain the increase in MPV in the patient with vitamin D deficiency: endothelial dysfunction and the inflammatory state induced by vitamin D deficiency expressed as an increase in pro-inflammatory cytokines such as IL-6 and TNFα." (PMID 32759752, 2020). "On the other hand, it is known that vitamin D deficiency is associated with a pro-inflammatory profile (IL-1, IL-2, IL-6, or TNF-α) which is modulated by calcitriol." (PMID 31068933, 2019). "After adjusting for known baseline differences among the vitamin D groups, only increased IL-6 was associated (p = 0.02) with vitamin D deficiency, and for each doubling of IL-6 there is a 19% increase in the odds of being vitamin D deficient." (PMID 28464004, 2017). "In a study conducted on 100 normotensive and 100 pre-eclamptic women, both plasma vitamin D deficiency (OR 4.2, 95% CI: 1.4–12.8, p = 0.04) and interleukin-6 elevation (OR 4.4, 95% CI: 1.8–10.8, p < 0.01) were independently associated with PE." (PMID 28709403, 2017). "Vitamin D deficiency, also known as hypovitaminosis D, is positively associated with serum levels of inflammatory markers, such as IL-6, TNFα and C-reactive protein in obese participants." (PMID 28353634, 2017). "On the contrary, vitamin D deficiency is associated with high level of inflammatory factors such as IL-6, TNF-α, and C-reactive protein (CRP)." (PMID 25741510, 2015). "In vitamin D deficiency however, excessive inflammation, as reflected by high IL-6 levels, increases GPx1 activity as a means of reducing oxidative protein injury." (PMID 26020962, 2015). "Vitamin D deficiency increased IL-6 levels by 22% compared to AI females, thereby elevating GPx1 protein content by 29%." (PMID 26020962, 2015). "Moreover, on the 28th day there was a significantly higher IL-6 level in the subjects with vitamin D deficiency (< 20 ng/ml) than subjects with normal vitamin D level with median values 6.94 pg/ml vs. 4.09 pg/ml and p-value of 0.002." (PMID 40671161, 2025).
vitamin D deficiency (continued). "Urinary albumin excretion (127.05 to 104.81 μg/mg, p < 0.05), urine MCP-1/creatinine (99.38 to 89.57 ng/mmol, p < 0.05), urine TGF-β/creatinine (79 to 72.33 ng/mmol, p < 0.05), TNF-α (57.7 to 47.09 pg/mL, p < 0.05), IL-6 (44.04 to 39.88 pg/mL, p < 0.05) in vitamin D insufficiency/deficiency group." (PMID 40134933, 2025). "In particular, vitamin D deficiency may promote the production of pro-inflammatory cytokines such as interleukin-6 (IL-6) and tumor necrosis factor-alpha (TNF-α), leading to impaired kidney function and subsequent uric acid accumulation." (PMID 40805984, 2025). "Our findings suggest that TNF-α and IL-6 may be key mediators linking vitamin D deficiency to OA severity in older adults." (PMID 39940305, 2025). "Moreover, vitamin D deficiency has been linked to increased production of inflammatory mediators, including IL-6 and TNF-α, further exacerbating OA progression." (PMID 40584103, 2025). "Changes in cytokines (such as interleukin-1, interleukin-6, and tumor necrosis factor-α), adipokines (such as leptin and adiponectin), and calcium and vitamin D deficiency may also play a role in bone metabolism changes during weight loss." (PMID 39770498, 2024). "Vitamin D deficiency may also intensify immune and inflammatory responses by elevating pro-inflammatory cytokines, such as IL-6 and TNF-α, which are associated with disrupted sleep patterns and poor sleep quality." (PMID 39619283, 2024). "Based on the present study high levels of TNF-α and IL-6 as well as vitamin D deficiency in studied participants could disturb the MMP-9/TIMP-1 balance and lipid metabolism, leading to plaque formation/ rupture in predisposed CAD patients." (PMID 38357561, 2023). "This hypothesis was supported in a recent study that showed a high interleukin-6 level and vitamin D deficiency." (PMID 38813002, 2023). "The present study suggested that high levels of TNF-α and IL-6 and vitamin D deficiency in our studied patients could disturb the MMP-9/TIMP-1 balance and lipid metabolism, leading to plaque formation/ rupture in predisposed CAD patients." (PMID 38357561, 2023). "Vitamin D deficiency was reported to be associated with endothelial function impairment as well as with elevated expression of inflammation mediators such as nuclear factor κB (NFkB) and interleukin-6 (IL-6)." (PMID 35369303, 2022). "We aimed to evaluate the relationship between the levels of vitamin D and adropin, IL-1β, IL-6 and oxidative status, which, we think might affect the pathological and metabolic conditions seen in vitamin D deficiency." (PMID 36326375, 2022). "Notably, a severe vitamin D deficiency has been found associated with increased expression of inflammatory cytokines, particularly interleukin-6 and tumor necrosis factor-α, both previously reported to increase the risk of DSPN." (PMID 35474356, 2022). "Severe vitamin D deficiency status may play a role in the painful DPN pathogenesis through elevated IL-6 and TNF-α levels." (PMID 33777989, 2021). "In children, where vitamin D deficiency and insufficiency is much more prevalent than in adults, there has been a link between vitamin D deficiency and oxidative stress and inflammation through surrogate molecules, such as cathepsin, IL-6, and adiponectin." (PMID 33572397, 2021). "Meanwhile, a small 12-week prospective trial showed reduction of IL-6 production via supplementation of vitamin D deficiency with 25OH-vitamin D, another placebo-controlled study with the same approach neither showed changes in cytokine production nor monocyte CD14/CD16 population distribution." (PMID 32455723, 2020). "Observations in a small patient number with vitamin D deficiency suggested that repletion might influence monocyte activity as serum levels of inflammatory leucocyte-derived cytokines, such as IL-8, IL-6, and TNF-α, were decreased." (PMID 32455723, 2020).